PNLIP (pancreatic lipase)
Diseases named in the same sentence as PNLIP in open-access papers (continued):
Sharing a sentence is not in itself a finding about the gene and the disease.
type 2 diabetes (11 papers, 2018 to 2025). "It has been reported that HJD has a strong lipid-regulating effect on type 2 diabetic rats, which can reduce the increase of pancreatic lipase activity in intestinal tract and inhibit the activity of pancreatic lipase in vitro." (PMID 33424585, 2020). "For instance, several natural-based enzyme inhibitors, such as orlistat (pancreatic lipase inhibitor), acarbose (α-glucosidase), and galantamine (AChE inhibitor), have already been used to treat some major diseases, such as type-2-diabetes mellitus (T2DM), Alzheimer’s disease (AD), and obesity." (PMID 37836131, 2023).
Hypercholesterolemia (10 papers, 2015 to 2025). An increased concentration of cholesterol in the blood. "Notably, inhibiting the activity of triglyceride-hydrolyzing enzymes, such as cholesterol esterase and pancreatic lipase, has emerged as a viable strategy for managing hypercholesterolemia and mitigating its associated complications." (PMID 40265934, 2025). "However, two enzymes (cholesterol esterase (CEase) and pancreatic lipase (PL) have been associated with hyperlipidemia and hypercholesterolemia complications, and their inhibitory potentials have been targeted by scientists in order to develop anti-hypercholesteremic drugs." (PMID 36981252, 2023). "Opuntia ficus-indica extract (OFIE) was tested on the inhibitory activity of pancreatic lipase enzyme (in vitro) and on hypercholesterolemia induced in mice by intraperitoneal administration of Triton WR-1339 (in vivo)." (PMID 39065815, 2024). "Therefore, OFIE prevents hypercholesterolemia by pancreatic lipase inhibition, partly attributed to its polyphenolic compounds." (PMID 39065815, 2024).
chronic pancreatitis (6 papers, 2015 to 2025). A chronic inflammatory process causing damage and fibrosis of the pancreatic parenchyma. "A recent study identified human PNLIP variants P245A, I265R, F300L, S304F, and F314L in European cohorts with chronic pancreatitis." (PMID 39265662, 2024). "Mutations that diminish PNLIP secretion can lead to rare diseases such as pancreatic lipase deficiency and chronic pancreatitis." (PMID 39265662, 2024). "The protease-sensitive PNLIP phenotype was strongly correlated with chronic pancreatitis, suggesting a novel pathological pathway underlying the disease." (PMID 39265662, 2024). "Owing to the structural similarities, we considered the mouse PNLIP as a suitable candidate to study the biological effects of the mutations of the human ortholog identified in chronic pancreatitis." (PMID 39265662, 2024). "More recently, four additional uncommon heterozygous PNLIP mutations (A174P, G233E, C254R and V454F) characterized by defective lipase secretion and incomplete penetrance were described in European chronic pancreatitis cohorts." (PMID 35704637, 2022). "The mutations induced intracellular PNLIP misfolding and ER stress, which increased susceptibility to chronic pancreatitis." (PMID 35704637, 2022). "Recently, we identified a subset of rare heterozygous PNLIP mutations, in both chronic pancreatitis patients and healthy controls with reduced lipase secretion." (PMID 35704637, 2022). "Pancreatic lipase is four times more active than amylase and it is less affected by exocrine pancreatic deficiency occurring in patients of chronic pancreatitis." (PMID 26345247, 2015). "Recently, rare heterozygous PNLIP mutations were reported in European chronic pancreatitis cohorts." (PMID 39265662, 2024). "Missense mutations in pancreatic secretory enzymes such as CPA1, PRSS1, CEL and PNLIP may lead to protein misfolding and the development of ER stress, which may predispose to chronic pancreatitis." (PMID 35704637, 2022). "Our observations demonstrated that the combination of hydroquinone and misfolding pancreatic lipase variant promote increased levels of endoplasmic reticulum stress and cell death, which may predispose to chronic pancreatitis." (PMID 35704637, 2022). "Given the fact that both genetic predisposition, and smoking can cause chronic pancreatitis via ER stress, we used the G233E misfolding PNLIP variant as an example, and examined if the detrimental effects of secretory protein misfolding and HQ cooperatively enhance the susceptibility to the disease." (PMID 35704637, 2022). "Still, the findings of low levels of fecal elastase and the potential for PNLIP variants to cause chronic pancreatitis suggest clinicians caring for these patients should be aware of the possibility that these patients may develop chronic pancreatitis, especially as they age." (PMID 40840699, 2025). "Although our Pnlip p.T221M mice develop chronic pancreatitis supporting the hypothesis that PNLIP p.T221 M can increase the risk for chronic pancreatitis through a protein misfolding and ER stress-related mechanism, differences between mouse and human are widely recognized." (PMID 40840699, 2025). "The relative abundance of A. muciniphila was increased by pancreatic enzyme therapy in chronic pancreatitis subjects, supporting a close relationship between pancreatic lipase activities and the modulation of intestinal microbiota." (PMID 32824369, 2020). "Interestingly, abdominal pain, a common symptom in chronic pancreatitis, is not prominent in patients with misfolding PNLIP variants." (PMID 40840699, 2025).
Insulin resistance (5 papers, 2017 to 2023). Increased resistance towards insulin, that is, diminished effectiveness of insulin in reducing blood glucose levels. "P. niruri decreased insulin resistance, reduced serum fatty acids, and inhibited α-glucosidase, pancreatic lipase and cholesterol micellization, leading to a decrease in the amounts of glucose and FFAs in the liver." (PMID 28718838, 2017). "TG metabolism is associated with inflammation and insulin resistance; moreover, even if TGs are not inherently toxic to the pancreas, their breakdown into FFAs by pancreatic lipase causes lipotoxicity." (PMID 35453916, 2022).
ischemia (5 papers, 2021 to 2025). A hypoperfusion of the BLOOD through an organ or tissue caused by a PATHOLOGIC CONSTRICTION or obstruction of its BLOOD VESSELS, or an absence of BLOOD CIRCULATION. "Excess triglycerides hydrolyzed by pancreatic lipase can lead to accumulation of free fatty acids, resulting in pancreatic capillary damage and local tissue ischemia, and thus causing AP." (PMID 40385473, 2025). "Most common theories for the pathophysiology of HTG-AP include hydrolysis of TG by pancreatic lipase to free fatty acids leading to endothelial and acinar cell damage and ischemia, as well as hyperviscosity related to increased chylomicrons." (PMID 36110119, 2022). "This could be due to the catalysis of TG by pancreatic lipase into free fatty acids (FFA), which induces ischemia and injury to pancreatic cells." (PMID 37301827, 2023).
atherosclerosis (4 papers, 2020 to 2025). A disease characterized by the build-up of fatty material and calcium deposition in the arterial wall resulting in partial or complete occlusion of the arterial lumen. "Liver proteomic analysis revealed downregulation of PXDN 9 (peroxidasin) and PNLIP (pancreatic lipase)—proteins associated with lipid oxidation and absorption—leading to enhanced lipid metabolism, reduced lipid peroxidation, and overall attenuation of atherosclerosis." (PMID 41155474, 2025). "Similarly, quercetin had a strong inhibitory activity on pancreatic lipase, and it also reduced serum levels of triglycerides and cholesterol in a rabbit model of high-fat diet-induced atherosclerosis." (PMID 32952589, 2020). "The present study investigated the effect of the leaves extracts and fractions of Plectranthus glandulosus on the inhibition of pancreatic lipase, cholesterol esterase, adipocytes lipid uptake, and antithrombotic activity which may be important in atherosclerosis development." (PMID 35178447, 2022).
exocrine pancreatic insufficiency (3 papers, 2022 to 2025). Inability of the exocrine pancreas to produce and secrete an adequate amount of digestive enzymes into the small intestine. "The coefficient of fat absorption in patients with exocrine pancreatic insufficiency who do not secrete pancreatic lipase is not zero, likely reflecting the activity of pre-pancreatic lipases." (PMID 41008568, 2025). "Additionally, a conference abstract described residual DGGR-lipase activity in dogs with exocrine pancreatic insufficiency, suggesting that DGGR is not solely hydrolysed by pancreatic lipase." (PMID 35448676, 2022).
pancreatic cancer (3 papers, 2017 to 2024). "Recently, gene PNLIP (pancreatic lipase) has been shown its association with the pancreatic cancer survival rate." (PMID 28198679, 2017). "The detected pathways will be useful for our further understanding of the role of gene PNLIP in pancreatic cancer research." (PMID 28198679, 2017). "Understanding these molecular changes can help us further investigate the role of gene PNLIP and even the general disease mechanism of pancreatic cancer." (PMID 28198679, 2017). "We divided the data set into a series of non-overlapping subsets according to the tumor/non-tumor paired expression ratio of gene PNLIP (pancreatic lipase, recently shown it association with pancreatic cancer)." (PMID 28198679, 2017).
pancreatic disease (3 papers, 2021 to 2024). "Feline pancreatic lipase immunoreactivity concentration is often used as tool for diagnosis of pancreatic disease but, recent studies reveal that it can be elevated both in pancreatitis and pancreatic neoplastic disease in cats." (PMID 36246338, 2022). "Serum feline pancreatic lipase immunoreactivity (fPLI) and trypsin‐like immunoreactivity (fTLI) concentrations are commonly used in cats for the evaluation of pancreatic disease." (PMID 34738673, 2021). "The workflow for diagnosing pancreatic disease in cats includes: a complete blood work-up, specific biochemical tests (e.g., feline pancreatic lipase immunoreactivity concentration), and abdominal ultrasonography, followed by a computed tomography (CT) scan and/or histopathology or cytopathology." (PMID 36246338, 2022). "However, the measurement of pancreatic lipase concentration has several limitations, as it can be elevated in some infectious diseases, intervertebral disc disease, foreign bodies, gastric dilatation and volvulus, and in some extra pancreatic diseases." (PMID 39716313, 2024).
cholelithiasis (2 papers, 2022 to 2024). The presence of crystallized deposits forming in the gallbladder or biliary tree, primarily composed of cholesterol, bilirubin, and bile. "Orlistat reduces intestinal absorption of fat content from food, as it is a pancreatic lipase inhibitor; side effects of this drug include diarrhea, oily stools, abdominal pain and, less frequently, cholelithiasis, cholestatic hepatitis, and subacute hepatitis." (PMID 35267958, 2022).
colitis (2 papers, 2021 to 2025). Inflammation of the colon. "In the mice with DSS-colitis, no significant alteration of pathological, histological (e.g., inflammatory cell accumulation), or physiological (e.g., expression of pancreatic lipase) conditions were found in the pancreas." (PMID 33594081, 2021).
colon carcinoma (2 papers, 2023 to 2025). "Notably, it showed the strong inhibition of pathogenic microbes, pancreatic lipase, and colon cancer (Caco-2) cell viability." (PMID 40573801, 2025).
heart failure (2 papers, 2025 to 2026). Inability of the heart to pump blood at an adequate rate to meet tissue metabolic requirements. "To understand this, here we study doxorubicin-induced heart failure, experimental AP, or pancreatic lipase-induced visceral fat necrosis in lean, genetically obese (ob/ob), or dual ob/ob pancreatic triglyceride lipase (PNLIP)-knockout mice." (PMID 40460832, 2025). "Determining if pancreatic lipase inhibition can improve heart failure outcomes is important since such therapy has entered clinical trials (ClinicalTrials.gov ID NCT06080789)." (PMID 40460832, 2025). "Their experimental models demonstrated that pancreatic injury can aggravate heart failure through excessive fatty acid release driven by pancreatic lipase-mediated fat necrosis, while pharmacologic inhibition or genetic deletion of pancreatic lipases prevents this deterioration." (PMID 41550778, 2026). "Here, we note that pancreatic injury may worsen heart failure from excess fatty acids generated by pancreatic lipases during fat necrosis and that pancreatic lipase inhibition or genetic deletion prevents such an exacerbation." (PMID 40460832, 2025). "While being broad and including over 4 million patients, this may have missed patients with painless lipase elevation and heart failure, thus underestimating the recently shown deleterious role of pancreatic lipase, which hydrolyzes triglycerides and worsens organ failure." (PMID 40460832, 2025). "The pancreatic lipase PNLIP enters adipocytes and rapidly hydrolyzes their lipid droplets, generating excessive non-esterified fatty acids that worsen heart failure." (PMID 40460832, 2025).
pancreatic lipase deficiency (2 papers, 2014 to 2025). "Congenital pancreatic lipase deficiency (CPLD, OMIM #614338) is a rare medical condition typically presenting with symptoms such as steatorrhea, fat-soluble vitamin deficiency, and low pancreatic lipase activity beginning in late infancy." (PMID 40840699, 2025). "Congenital pancreatic lipase deficiency (CPLD, OMIM #614338) is a rare exocrine pancreatic disorder presenting in late infancy with steatorrhea, fat-soluble vitamin deficiency, and low pancreatic lipase activity." (PMID 40840699, 2025).
vitamin deficiencies (2 papers, 2025). "EPI becomes clinically apparent when pancreatic lipase levels aremarkedly reduced, often accompanied by multiple markers of malnutrition,including weight loss, vitamin deficiencies, electrolyte imbalance,osteoporosis, and osteomalacia, resulting in bone fractures." (PMID 41337569, 2025).
Anorexia (1 paper, 2021). Lack of desire to eat (loss of appetite). "Long-term exposure to AFB1 can lead to chronic poisoning and decrease the activities of digestive tract enzymes, pancreatic lipase, trypsin, amylase, and other enzymes, resulting in nutritional absorption disorders, metabolic disorders, and anorexia, thus causing slow growth of body weight." (PMID 34769051, 2021).
Constipation (1 paper, 2024). Infrequent or difficult evacuation of feces. "The present results suggest that C3 deficiency-induced constipation may be associated with 1237 upregulated genes including PNLIP, CEL, CPB1, CTRL, PNLIPRP1, and REG1 as well as 1292 downregulated genes including Eif2s3y, UTY, KDM5D, IGKV6-32, Olfr870, and DDX3Y." (PMID 39273477, 2024).
diverticulitis (1 paper, 2025). An infection that develops in the diverticula of the intestinal tract. "Fat necrosis in AP contained significantly higher activity of pancreatic lipase and PLA2 compared with diverticulitis and also had higher NEFA concentrations (6,636 ± 1,973 μM)." (PMID 40460832, 2025).
fecal incontinence (1 paper, 2023). Involuntary passage of stool from the rectum. "This particular mechanism of action makes orlistat’s inhibitory impact on pancreatic lipase highly potent and irreversible, thereby leading to adverse effects such as abdominal discomfort, fecal incontinence, and steatorrhea." (PMID 37836509, 2023).
gastroesophageal reflux (1 paper, 2019). "There is also the potential that gastric lipase or even pancreatic lipase have reached the oral cavity by gastroesophageal reflux or duodenogastro-oesophageal reflux respectively and thus would account for the measured lipolytic activity." (PMID 30669294, 2019).
Hyperinsulinemia (1 paper, 2024). An increased concentration of insulin in the blood. "Nevertheless, targeting IRE1α RNase activity normalized blood glucose concentrations in both BI-1–/– and WT mice fed HFD, reduced hyperinsulinemia and pancreatic lipase levels, reflecting an improvement in glucose homeostasis and β-cell function." (PMID 38744890, 2024).
Hypocalcemia (1 paper, 2024). An abnormally decreased calcium concentration in the blood. "Patients with hypocalcemia resulting from gastric bypass and hypoparathyroidism have been effectively treated using oral vitamin D and calcium supplements, intravenous calcium gluconate infusions, calcium administered via gastrostomy, and, in rare instances, pancreatic lipase therapy." (PMID 39411620, 2024).
intestinal obstruction (1 paper, 2018). Blockage of the normal flow of the intestinal contents within the bowel. "Canine pancreatic lipase immunoreactivity values above 400 μg/L were detected in 6/22 dogs with gastric dilatation-volvulus and 4/16 with intestinal obstruction." (PMID 30226861, 2018).
steatosis (1 paper, 2024). Increased lipid within the cytoplasm of cells. "When the secretion of pancreatic lipase falls below 10%, there will be obvious steatosis and weight loss." (PMID 39604884, 2024).
metabolic disorders (12 papers, 2013 to 2025). "Pancreatic lipase is a key lipase for triacylglyceride digestion and absorption, which is recognized as a promising target for treatment of metabolic disorders." (PMID 34025435, 2021). "The pancreatic lipase inhibitors could produce hypolipidemic activity, which could be useful for control or treatment of metabolic disorders." (PMID 34025435, 2021). "Up to now, several herbal medicines, such as Citri Reticulatae Pericarpium and Mori Radicis Cortex, have been demonstrated with strong inhibition on pancreatic lipase for the regulation of lipid metabolism, which are applied to treat hyperlipidemia and other metabolic diseases in clinic." (PMID 34025435, 2021). "The pancreatic lipase is secreted from the pancreas, and it has been demonstrated that inhibition on pancreatic lipase and regulation of lipid absorption is an effective approach for discovering new agents for treatment of metabolic disorders." (PMID 34025435, 2021).
cancer (8 papers, 2012 to 2025). A tumor composed of atypical neoplastic, often pleomorphic cells that invade other tissues. "This study aimed to develop a novel Acrocomia aculeata (bocaiuva) fruit pulp oil-loaded nanoemulsion and evaluate its inhibitory effects on α-glucosidase and pancreatic lipase, as well as its antiglycant activity and cytotoxicity against cancer cells." (PMID 40872486, 2025). "Compound 4 was formerly reported to have inhibitory activity against diverse human cancer cells, but did not hamper α-glucosidase and pancreatic lipase activities." (PMID 35889842, 2022). "Among them, pancreatic lipase is significantly reduced in PDAC and may be a predictor of cancer mortality." (PMID 34707986, 2021).
tumor (6 papers, 2012 to 2024). "Wound healing, anxiolytic, anti-tumor, antibacterial, anti-fungal, anti-hyperlipidemic, antioxidant, postpartum anti-hemorrhagic, pancreatic lipase inhibitor, and cytotoxic activities." (PMID 38675115, 2024). "Serum lipase levels were monitored on the blood of the xenografts to examine pancreatic lipase secretion compared to tumor volume." (PMID 27165126, 2016). "Although initially the inhibitory properties of orlistat were demonstrated for pancreatic lipase, a large survey of a number of tumor and normal cell lines has lead to the conclusion that orlistat has no other targets than FASN in tumor cells, and that has minimal effects on the normal cells." (PMID 23029529, 2012). "Although the FDA‐approved FASN inhibitor, Orlistat, is shown to be effective in reducing tumor cells in vivo, one main limitation is its extremely low oral bioavailability, as Orlistat exerts its effects primarily in the gastrointestinal tract, where it inactivates pancreatic lipase." (PMID 29449326, 2018).